GZMB (granzyme B)
Diseases named in the same sentence as GZMB in open-access papers (continued):
Sharing a sentence is not in itself a finding about the gene and the disease.
tumor (continued). "The host non‐CAR tumor‐infiltrating CTLs in the mice treated with RARα‐KO CAR‐T cells had elevated expression of IFN‐γ, GzmB, and Perforin." (PMID 40068101, 2025). "Within the tumor tissues, more CD8+ T cells were activated by SAN-TLRa vaccination and BMAA treatment, shown by the increased Granzyme B+ (GzmB+) and IFN-γ+ CD8+ T cells." (PMID 40083927, 2025). "In certain contexts, CD4+ T cells can also acquire cytotoxic potential via expression of perforin and granzyme B, directly killing MHC class II+ tumor cells." (PMID 40660400, 2025). "The tumor-infiltrating CD8 T cells acquired an effector phenotype, evidenced by increased expression of the cytotoxic mediator granzyme B and decreased expression of the anti-inflammatory and pro-tumor cytokine TGFβ1." (PMID 40315226, 2025). "pDC enables the expression of the cytotoxic molecules granzyme B and TRAIL, induces cDC1 maturation, and enhances the function of CD8+ T cells and NK cells in the TME, hence blocking tumor growth." (PMID 40297580, 2025). "CD4+ T28zT2 T cells upregulated NKG2D within tumors and suppressed tumor growth by producing IFN-γ and Granzyme B. Previous studies consistently report that TGF-β1 suppresses the expression of NKG2D in T cells and NK cells." (PMID 40107245, 2025). "This synergistic effect depended on CD8+ T cell activity, as reflected by increased granzyme B (GZMB) expression during combination therapy, suggesting a positive modulation of the tumor immune microenvironment by chemo‐IT." (PMID 40900811, 2025). "Knockdown of RFWD3 inhibited proliferation and increased secretion of IFN‐β at the cellular level, and repressed tumor growth with an increase in CD4+, CD8+, Granzyme B+/CD8+, IFN‐γ/CD8+, NK, and DC cells and a decrease in MDSCs." (PMID 41117130, 2025). "CAR T cell-induced pyroptosis further illustrates this complexity: granzyme B activates caspase-3 and GSDME in tumor cells, which triggers caspase-1-dependent GSDMD in macrophages, causing cytokine release syndrome." (PMID 41291696, 2025). "Our research found that treatment with 2-Met or deletion of USP13 in tumor cells led to significantly increased CD8 + T cell infiltration, along with elevated GZMB and IFN-γ secretion, indicating enhanced T cell activity." (PMID 41330897, 2025). "Subsequent FCM analysis of the tumor-infiltrating CD8+ T cells in the mice revealed increased expression of INFγ, TNF-α, and GzmB across all treatments, with the combined treatment showing the most pronounced effects." (PMID 40365283, 2025). "Some of these changes, including tumor reactive CD8+ T cells that express CD11, Granzyme B, and CX3CR1 and classical regulatory T cells, predicted clinical outcomes despite the limited number of patients in the study." (PMID 40082438, 2025). "This subset had the capacity to migrate to the tumor and differentiate into a TCF-1- TIM-3+ GZMB+ effector-like population." (PMID 40229241, 2025). "mHTV-02 immunization increased the infiltration of multifunctional (IFN-γ+ GzmB+) CD8+ T cells and effector memory CD4+ and CD8+ T cells to the tumor." (PMID 41012179, 2025). "When comparing NK cell subsets within the tumor compartment, we observed that ILC1-like cells displayed significantly lower levels of perforin A and granzyme B expression compared to cNK cells." (PMID 41268557, 2025). "Loss of NLRP3 disrupted this process, leading to heightened Th17 inflammatory output (IFN-γ, Granzyme B, TNF-α) and restored CD8+ T-cell cytotoxicity, ultimately constraining tumor growth." (PMID 41291696, 2025). "HMGB2 silencing or knockout enhanced NK cell cytotoxicity, evidenced by increased granzyme B, perforin, IFN-γ, and TNF-α, and higher tumor cell lysis." (PMID 41280896, 2025). "Moreover, LTS showed an increased expression of antitumor immune markers such as CD8+, CD3+ and Granzyme B+ cells within the tumor, suggesting the intratumor microbiome may promote immune activation within the tumor microenvironment, promoting a more robust antitumor immune response." (PMID 40243755, 2025).
tumor (continued). "Secreted GDF15 activates JNK signaling, downregulating the NK cell-killing essential receptor NKG2D and the effector molecule granzyme B (GZMB), thereby impairing NK cell cytotoxicity and enabling tumor cells to evade immune surveillance." (PMID 41020873, 2025). "Cytotoxic CD8+ T cells are abundant within the TME and play a pivotal role in anti-tumor immunity by secreting granzyme B and interferon-γ (IFN-γ) to eradicate tumor cells." (PMID 40534863, 2025). "The cytotoxic functions of CTLs, such as granzyme B, perforin, IFN-γ, FasL (CD95L), and TNF-⍺, are elevated by induced hyperthermia, as is Fas receptor presentation on tumor cells." (PMID 41375025, 2025). "SRSF1-sh tumor cells exhibited strong signals for both IFN-γ and GZMB, in contrast to control tumors, which produced minimal amounts of these cytokines." (PMID 39837814, 2025). "In vivo, anidulafungin significantly increased serum levels of IFN-γ and IL-4 in tumor-bearing mice and elevated expression of IFN-γ and granzyme B (GZMB) in tumor tissues, confirming its immune-mediated anti-tumor effects." (PMID 40872601, 2025). "This LY6A+ CD314+ subset can migrate to the tumor and differentiate into TIM-3+ GZMB+ TCF-1- effector-like cells." (PMID 40229241, 2025). "In vivo experiments further confirmed that silencing USP13 led to a significant reduction in tumor size, accompanied by an increase in both CD8 + T cell infiltration and the expression levels of GZMB and IFN-γ within the tumor tissue." (PMID 41330897, 2025). "Immunofluorescence analyses revealed co-localization of CD8+ T cells with GZMB and IFN-γ, confirming that infiltrating T cells are functionally activated—a key determinant of anti-tumor efficacy." (PMID 41373467, 2025). "CD8+ effector T cells (cytotoxic T lymphocytes, CTLs) serve as key mediators of antitumor immunity by recognizing tumor cells through MHC class I molecules and inducing apoptosis through the release of perforin‐1 (PRF1), granzyme B (GZMB), and IFN‐γ." (PMID 40859981, 2025). "Consistently, I3A treatment significantly increased the presence of tumor‐infiltrating CD8+ T cells in B16 tumors, concomitant with an elevated level of GZMB expression on these infiltrated cells, suggesting immune activation in the tumor microenvironment." (PMID 40583248, 2025). "For instance, granzyme B (GZB), a key effector molecule involved in tumor cell death, serves as a valid biomarker for T-cell-mediated cytotoxicity and the anti-tumor response." (PMID 41011180, 2025). "Pre-clinical data show that PD-1 blockade (nivolumab) enhanced CAR-iNKT proliferation, cytokine production (IL-2, TNF-α, IFN-γ, and granzyme B) and effectively reversed CAR-iNKT exhaustion upon tumor rechallenge, translating into deeper tumor control." (PMID 40718496, 2025). "CD8+ T cells mediate antitumor immunity by recognizing and killing tumor cells through MHC class I-restricted antigen presentation, as well as releasing cytotoxic molecules such as Perforin and Granzyme B." (PMID 40507854, 2025). "The identification of cytolytic enzyme expression levels (perforin, granzyme A, granzyme B, granzyme K, and IFN-γ) provided further insights into the anti-tumor functions of these T cells." (PMID 39979981, 2025). "We then analyzed the immune cell infiltration in the tumor microenvironment (TME) and found that the percentage of tumor-infiltrating effector CD8+ T cells, which express IFN-γ, GzmB, and CD44, was elevated in L-SeMet-treated mice." (PMID 40141154, 2025). "We examined the levels of INF-γ, Granzyme B, and PD-1 in human PBMCs that had been injected with either WT-A549 or PRKCSH-KO A549 cells to investigate how T cells killed tumor cells and how the immune system was activated." (PMID 41350724, 2025). "Single-cell suspensions of tumor tissues were further analyzed by flow cytometry, which demonstrated a significantly higher proportion of CD8+granzyme B+ T cells in cKO mice than in WT mice (p = 0.0449)." (PMID 40735646, 2025).
tumor (continued). "Particularly, we evaluated the dynamics of tumor infiltration by immune cells expressing CD4, CD8, and granzyme B (GrB)." (PMID 40007542, 2025). "Cytotoxic CD8+ T cells (CTLs) bind to MHC I and secrete cytokines such as granzyme B, perforin, IFN-γ, and TNF-α as well as mediate tumor cell apoptosis through FasL/Fas interaction." (PMID 40458394, 2025). "Similar to the results observed in the subcutaneous xenograft model, the mCAR-T group had more CD3+ and Granzyme B+ cells in the tumors, reduced CD133 expression, and increased PD-L1 expression in the tumor cells compared to the CAR-T group." (PMID 40612678, 2025). "Emodin effectively reduced PD-L1 levels in H22 cells and increased anti-tumor activity in an H22 subcutaneous tumor model by promoting CD8+ T cells infiltration and TNF-α, IFN-γ, and granzyme B secretion." (PMID 40804393, 2025). "Mechanistically, human ILC2s can produce the cytotoxic molecule Granzyme B (GZMB) and directly lyse tumor cells by inducing pyroptosis and/or apoptosis, which is governed by DNAM-CD112/CD155 interaction." (PMID 39858045, 2025). "ICB responsive tumors contained abundant granzyme B+ T cells, whereas ICB resistant tumors were characterized by CD15+ tumor cells." (PMID 41425696, 2025). "NK cells, as core effector cells of the innate immune system, exert anti-tumor functions through the activation of surface receptors such as NKG2D and the release of cytotoxic molecules, including Granzyme B and Perforin." (PMID 41357886, 2025). "NK cell-derived granzyme B cleaves GSDME at the same site as caspase-3, and co-culture with NK cells enhanced GSDME cleavage in tumor cells." (PMID 41144149, 2025). "Spatial co-localization analysis confirmed that low Streptococcus abundance in tumor-adjacent regions directly correlated with reduced CD8+ T-cell infiltration (p < 0.01) and lower IFN-γ/Granzyme B expression (p < 0.01)." (PMID 41438381, 2025). "TIGIT+ CD8+ T cells exhibit reduced levels of effector molecules such as IFN-γ, perforin, and granzyme B, indicating functional impairment and supporting TIGIT’s role in promoting T cell exhaustion within the tumor microenvironment." (PMID 41300994, 2025). "We found that emodin treatment enhanced anti-tumor effects by increasing CD8+ T cells infiltration and promoting TNF-α, IFN-γ, and granzyme B (Gzms-B) secretion." (PMID 40804393, 2025). "Regarding cytotoxicity-related genes, GZMB and SYTL3 were up-regulated in the NK1 cluster, while PFR1 (perforin) and TNFSF10 (TRAIL) were down-regulated in tumor-infiltrating iNK cells as compared to preinfusion iNK cells." (PMID 40315330, 2025). "Anti-MUC1-CAR4 T cells achieve anticancer effects on MUC1-expressing CCA cells by increasing the production of anti-tumor cytokines (TNF-α and IFN-γ), pro-apoptotic proteins (granzyme B), and by inducing lysis of CCA cells." (PMID 40070825, 2025). "This study explored the role of perforin-1 (PRF1) and granzymes A, B and K (GZMA, GZMB and GZMK) in cancer biology, focusing on their impact on tumor cell death and immune response modulation." (PMID 40002821, 2025). "In the tumor microenvironment of the solid tumor, tumor-infiltrating lymphocytes kill cancer cells by producing cytokines, such as, interferon-gamma (IFN-γ), granzyme B, and tumor-necrosis factor-alpha (TNF-α)." (PMID 40169858, 2025). "In this study, treatment with GHSACA resulted in a marked increase in granzyme B–positive cells and enhanced infiltration of CD8+ T cells within the tumor." (PMID 41488675, 2025). "Flow cytometry analysis revealed that combination treatment with H151 and TZ‐dSA3‐12 reduced tumor‐infiltrating CD8+ T cells and diminished GzmB and IFN‐γ production compared to TZ‐dSA3‐12 treatment group." (PMID 40492586, 2025). "The impact of this combination therapy on the tumor immune microenvironment was assessed via immunofluorescence staining of tumor sections for CD8, PD-1, and Granzyme B." (PMID 40605065, 2025).
tumor (continued). "The function of CD8+ T cells in tumor tissues was also altered, with a significantly lower level of secretion of IFN-γ and granzyme B. This resulted in the over-exhaustion of CD8+ T cells in the TME." (PMID 40040705, 2025). "In support of these results, IF staining of primary tumours revealed a significant increase in total CD8 + T cell numbers, and cytotoxic GzmB+CD8 + T cells upon VISTA blockade suggesting enhanced cytotoxic activity." (PMID 40316725, 2025). "By bridging IL-13Rα2+ tumor cells and CD3ε on T cells, the BiTE induces T-cell activation (CD69/CD25 upregulation), GZMB release, and production of inflammatory cytokines (IFN-γ, TNF-α), culminating in tumor-specific lysis." (PMID 41209565, 2025). "Significant enrichment in tumor-blood matched TCR clusters was also seen in cytotoxic CD8+ (GZMK+, GZMB+, and MAIT) T cells." (PMID 40299576, 2025). "The expression of effector molecules granzyme B and IFN-γ exhibited substantial upregulation in tumor tissues and infiltrating T cells, suggesting potentiated anti-tumor cytotoxicity." (PMID 41345744, 2025). "DNT have been shown to effectively eliminate tumor cells in both hematologic malignancies and solid tumors through multiple pathways, including direct cytotoxicity via IFN-γ, perforin, and granzyme B secretion." (PMID 41168829, 2025). "In pre-cancerous mammary lesions, IL-15 secreted by tumor cells was shown to induce GzmB production in CD103+ cytotoxic ILC1s, contributing to early tumor surveillance." (PMID 40963622, 2025). "GMDP signals through NOD2 on myeloid cells to release IL-1b and NLRP3 to induce cytotoxic granzyme B+CD8+ T cells in the tumor and enhances the efficacy of anti–CTLA-4, anti–PD-1, and anti–PD-L1 in different mouse tumor models." (PMID 39895632, 2025). "uPA deficiency resulted in increased CD8+ T-cells infiltration and cytotoxicity via increasing GzmB, IFN-γ, and TNF-α secretion, further suppressing tumor growth." (PMID 40959092, 2025). "GPC2-directed CAR T cells demonstrated early and sustained activation in tumor co-culture, with increased intracellular interferon (IFN)-γ detected at 12 h and elevated granzyme B (GZMB) levels by 36 h." (PMID 41159102, 2025). "This is consistent with the classical model in which GZMB acts in cytotoxic T lymphocytes (CTL) and NK cells, leading to the elimination of tumor cells." (PMID 40766321, 2025). "Tumor-infiltrating CD8 T cells from Sert-KO BMT mice displayed enhanced effector function (i.e., higher IFN-γ and Granzyme B production) and decreased exhaustion markers (i.e., PD-1)." (PMID 40403728, 2025). "Although Y45 increased granzyme B release, CD8+ T cells remained predominantly at the tumor edge, limiting their antitumor effect." (PMID 40108893, 2025). "Accordingly, tumor-infiltrated CD8+ T and NK cells, especially those with effector phenotypes (granzyme B and CD25) in mice treated with αNKG2A-N215 were significantly more numerous than those in mice treated with the combination therapy of αNKG2A and N215." (PMID 40170468, 2025). "Activated granzyme B (GzmB)-expressing CD8+, CD4+ TEM and CD4+ Treg cells were also abundant (91%, 37% and 27%, respectively) in the posttreatment tumor." (PMID 40016450, 2025). "GZMB, secreted by CD8+ cytotoxic T lymphocytes (CTLs), induces tumour cell apoptosis, and co‐stimulatory molecule CD28 is crucial for the proliferation, activation, cytokine production and development of CD8+ T cells." (PMID 40356247, 2025). "The expressions of IFN‐γ, TNF‐α, and GzmB were significantly increased, while PD‐1 was dramatically decreased in CD8+ T cells from tumor tissues of BMDMsPRDX1‐KO group compared to the BMDMsWT group." (PMID 41306557, 2025). "Tumor cells induce H3K9me3 deposition at the promoter of G6PD, resulting in decreased G6PD and granzyme B expression in tumor-specific cytotoxic T cells." (PMID 39859324, 2025).
tumor (continued). "In contrast, within the Tumor-Immune enriched neighborhood (comprising ~50% tumor and ~50% stromal/immune cells), CD8+T- cells were enriched for Granzyme B and PD-1 whereas CD4+T- cells in this neighborhood were enriched for ICOS and PD-1." (PMID 41254766, 2025). "Tumor-infiltrating CAR+CD8+ T cells from the T4M828zT2 group lysed AsPc-1 cells more efficiently, produced more IFN-γ and Granzyme B, and expanded faster than those from the M28zT2 or 1928zT2 groups." (PMID 40107245, 2025). "In non-clinical studies using cancer model mice, anti-CCR8 antibodies were shown to deplete tumor-infiltrating Tregs, increase CD8+ T cell infiltration within tumors, and enhance CD8+ T cell functions by upregulating GzmB and IFN-γ expressions 14,17." (PMID 41323783, 2025). "Conversely, elevated ceramide levels promoted increased T cell activation and improved granzyme B production in CD8+ T cells, enhancing their cytotoxic function and anti-tumoral immune response, which ultimately resulted in reduced tumor growth." (PMID 40597360, 2025). "This robust anti-tumor effect correlated with the increase in intratumoral CD40 + DCs and the frequency of granzyme B+/IFN-γ+/TNF-α+ polyfunctional antigen-specific CD8 + T cells." (PMID 40500288, 2025). "In conclusion, our findings demonstrate that P. aeruginosa sensitizes cells to αPD-1 for the treatment of CRC mediated anti-tumor immune responses by activating cytotoxic CD8+ T cells and upregulating Granzyme B expression." (PMID 40191185, 2025). "We employed immunostaining for CD3, CD4, CD8, Granzyme B (GzmB), FOXP3, CD163, and CD68 markers to quantitively analyze the STR patient’s tumor immune landscape both at baseline and during STR 10–12." (PMID 40594889, 2025). "NK-derived exosomes (NK Exos) carry a complex cargo of cytotoxic proteins (perforin, granzyme B, FasL, TRAIL), surface receptors (NKG2D), RNAs, and lipids that mediate direct tumor killing and immune modulation." (PMID 41511353, 2025). "Flow cytometry analysis of tumor‐infiltrating CD8+ T cells revealed that cotreatment with V‐9302 and anti‐PD‐1 significantly enhanced the expression of cytolytic proteins (GZMB and PRF1) and effector cytokines (IFN‐γ and TNF‐α) compared to monotherapy groups." (PMID 40575936, 2025). "Deletion of Vcp in tumor cells augmented the cytotoxicity of CD8+T cells, induced apoptosis in tumor cells, lessened CD8+T cell apoptosis, and upregulated the level of cytokines GzmB and IFN-γ, consistent with our in vivo observations." (PMID 39848960, 2025). "When coincubated with tumor cells, γδ CAR-T cells presented increased expression levels of CD69, TNF-α and granzyme B." (PMID 39939816, 2025). "Coupling TCR specificity with innate-like speed, iNKT cells are rapidly activated without requiring priming and demonstrate potent cytotoxicity (via perforin, granzyme B and FasL/CD95) against various tumor types." (PMID 40718496, 2025). "IHC staining was performed to assess the expression of CD8+ T cells, granzyme B, and CRT at the tumor site." (PMID 40498983, 2025). "Of note, in our study TSTEM-2 cells can migrate to the tumor and continue their differentiation into TIM-3+ GZMB+ cells potentially bypassing the TPEX intermediate state in the TdLN." (PMID 40229241, 2025). "By specifically cleaving these proteins, GZMB compromises ECM integrity, thereby facilitating tumor cell invasion and migration." (PMID 41567188, 2025). "Immunohistochemistry (IHC) confirmed elevated expression of the cytotoxic effector cytokines (GzmB, IFN-γ, TNF-α) in tumor tissues of uPA–/– mice, whereas ELISA confirmed increased serum levels of these cytokines in uPA–/– tumor-bearing mice." (PMID 40959092, 2025). "Cytotoxic CD4+ phenotypes (i.e., GZMB+, GZMK+, Prolif which is largely cytotoxic, and MAIT) comprised the vast majority of CD4+ cells in blood that matched a TCR with tumor." (PMID 40299576, 2025).